PLEKHO1 (pleckstrin homology domain containing O1)
Description:
Plays a role in the regulation of the actin cytoskeleton through its interactions with actin capping protein (CP). May function to target CK2 to the plasma membrane thereby serving as an adapter to facilitate the phosphorylation of CP by protein kinase 2 (CK2). Appears to target ATM to the plasma membrane. Appears to also inhibit tumor cell growth by inhibiting AKT-mediated cell-survival. Also implicated in PI3K-regulated muscle differentiation, the regulation of AP-1 activity (plasma membrane bound AP-1 regulator that translocates to the nucleus) and the promotion of apoptosis induced by tumor necrosis factor TNF. When bound to PKB, it inhibits it probably by decreasing PKB level of phosphorylation.
Synonyms: JBP; CKIP-1; CKIP1; OC120
Tractability: Antibody: UniProt places it where antibodies can reach, with high confidence; its Gene Ontology location is reachable by antibodies, with medium confidence. PROTAC: its protein half-life has been measured.
Gene: Protein-coding gene on chromosome 1 (150,149,183 to 150,164,720, forward strand). Ensembl gene ENSG00000023902.
Subcellular location: Cell membrane; Nucleus; Cytoplasm
Subcellular location (Human Protein Atlas): Mitochondria
Gene Ontology:
Molecular function: protein binding
Biological process: regulation of myoblast fusion
Cellular component: cytoplasm; mitochondrion; nucleus; plasma membrane; muscle cell projection membrane; ruffle membrane
Genetic constraint (gnomAD): Loss-of-function variants: 16 observed, 33.32 expected, observed/expected ratio (o/e) 0.48, 90% interval 0.32 to 0.73. The upper end of that interval is the gene's LOEUF score, 0.73, which puts it in group 2 of 6, group 1 being the genes least tolerant of losing a copy. Missense variants: 437 observed, 477.22 expected, observed/expected ratio (o/e) 0.92, 90% interval 0.85 to 0.99. Synonymous variants: 206 observed, 201.32 expected, observed/expected ratio (o/e) 1.02, 90% interval 0.91 to 1.15.
Homologues: Orthologues: chimpanzee PLEKHO1 (99% identical), macaque PLEKHO1 (97% identical), pig PLEKHO1 (96% identical), rabbit PLEKHO1 (92% identical), mouse Plekho1 (90% identical), dog PLEKHO1 (90% identical), rat Plekho1 (88% identical), guinea pig PLEKHO1 (79% identical), tropical clawed frog plekho1 (68% identical), zebrafish plekho1b (58% identical), zebrafish plekho1a (50% identical). Paralogues in human: PLEKHO2 (29% identical).
Diseases named in the same sentence as PLEKHO1 in open-access papers:
PLEKHO1 is named in the same sentence as 42 diseases in open-access papers, as found by Europe PMC text mining. Sharing a sentence is not in itself a finding about the gene and the disease. The quoted sentences say what the papers report.
osteoporosis (19 papers, 2015 to 2024). A condition of reduced bone mass, with decreased cortical thickness and a decrease in the number and size of the trabeculae of cancellous bone (but normal chemical composition), resulting in increased fracture incidence. "Hydrazone-cross-linked HA hydrogel incorporated with siRNAs against pleckstrin homology domain-containing family O member 1 (PLEKHO1) as a key causative of osteoporosis resulted in successful gene silencing and knockdown of protein expression with a low cytotoxicity in vitro." (PMID 37504467, 2023). "In conclusion, increasing PLEKHO1 can inhibit Smad-dependent BMP signaling, thereby inhibiting bone formation during aging, suggesting that PLEKHO1 has the potential to prevent osteoporosis in osteoblasts." (PMID 39871887, 2024). "Administration of Plekho1 siRNA encapsulated in the osteoblast-specific delivery system reversed established osteoporosis during aging in mice." (PMID 32071307, 2020). "Toward translational medicine, it indicates that targeting PLEKHO1 in osteoblasts may be a potential bone anabolic strategy to reverse established osteoporosis during aging." (PMID 28083909, 2017). "siRNA PLEKHO1 may be proposed as a possible treatment for osteoporosis." (PMID 37675799, 2023). "Taken together, it suggests that the increased PLEKHO1 could suppress Smad‐dependent BMP signaling to inhibit bone formation during aging, indicating the translational potential of targeting PLEKHO1 in osteoblast as a novel bone anabolic strategy for reversing established osteoporosis during aging." (PMID 28083909, 2017).
cardiac hypertrophy (10 papers, 2017 to 2024). "Previous studies reported that the PH domain-containing protein CKIP-1 (casein kinase 2-interacting protein-1, also known as PLEKHO1) played a role in the regulation of macrophage homeostasis, tumorigenesis, cardiac hypertrophy as well as cell apoptosis, cell morphology, and the actin cytoskeleton." (PMID 28404913, 2017).
gastric cancer (10 papers, 2017 to 2024). A primary or metastatic malignant neoplasm involving the stomach. "It has been shown that DUXAP8 can significantly inhibit the expression of PLEKHO1 in gastric cancer, enhancing the proliferation and migration of tumor cells." (PMID 34957112, 2021). "DUXAP8 can significantly inhibit the expression of PLEKHO1 in gastric cancer, which enhances the proliferation and migration of tumor cells." (PMID 34957112, 2021). "In gastric cancer, DUXAP8 could promote tumor growth by interacting with the PRC2 complex to inhibit PLEKHO1 expression." (PMID 32849765, 2020). "Moreover, DUXAP8 was also found to be over-expressed in human gastric cancer, and increased DUXAP8 promoted cells proliferation and invasion through epigenetically silencing PLEKHO1 expression by binding with EZH2 and SUZ12 in gastric cancer cells." (PMID 29152119, 2017).
colon cancer (6 papers, 2017 to 2025). "The prognostic relevance and underlying mechanism of PLEKHO1 in the immune microenvironment of colon cancer have also been reported." (PMID 40257955, 2025). "In addition, they showed that the downregulation of PLEKHO1 in colon cancers might be reversed by methylation of the promoter of the PLEKHO1 gene." (PMID 28881724, 2017).
leukemia (2 papers, 2017 to 2024). A malignant (clonal) hematologic disorder, involving hematopoietic stem cells and characterized by the presence of primitive or atypical myeloid or lymphoid cells in the bone marrow and the blood. "Cdkn2a-WT MYB::PLEKHO1 leukemias showed intact expression of p16INK4A and p19ARF, while Cdkn2a-KO leukemias did not, confirming that MYB::PLEKHO1 is indeed able to induce leukemia independently of Cdkn2a loss." (PMID 39499902, 2024). "In vivo ATRA treatment in secondary recipients of Cdkn2a-WT MYB::PLEKHO1 or Cdkn2a-KO MYB::PLEKHO1 leukemias resulted in a significant reduction in disease burden." (PMID 39499902, 2024). "Hoxb8-FL cell–derived MYB-TR and MYB::PLEKHO1-driven leukemias were positioned between myeloid progenitors, monocytes, and DCs, consistent with their surface protein marker expression." (PMID 39499902, 2024). "This revealed binding of MYB::PLEKHO1 to the transcription start sites of BPDCN-associated genes such as Il3ra (CD123), Bcl2, and Myc, which were strongly expressed in leukemia cells." (PMID 39499902, 2024). "Our findings confirm that, in a mouse model, expression of MYB::PLEKHO1 is sufficient to initiate leukemia in hematopoietic progenitor cells." (PMID 39499902, 2024). "MYB::PLEKHO1 can independently overcome G1/S arrest to induce leukemia." (PMID 39499902, 2024). "Hoxb8-FL cell–derived leukemia was almost fully penetrant in Cdkn2a-WT MYB::PLEKHO1, Cdkn2a-KO MYB-TR, and Cdkn2a-KO MYB::PLEKHO1 recipient mice but was rarely observed in other genotypes and only with significantly longer latency." (PMID 39499902, 2024). "To investigate why MYB::PLEKHO1 but not MYB-TR initiated leukemia in Cdkn2a-WT Hoxb8-FL cells, we developed a system to culture MYB-expressing Hoxb8-FL cells in vitro without requiring Hoxb8 activation." (PMID 39499902, 2024). "In contrast to MYB-TR, MYB::PLEKHO1 did not require Cdkn2a KO to initiate leukemia in Hoxb8-FL cells." (PMID 39499902, 2024).
renal cell carcinoma (2 papers, 2024 to 2025). "PLEKHO1 contributes to the development of renal cell carcinoma, and its knockdown significantly inhibits cancer cell viability while promoting apoptosis." (PMID 40257955, 2025).
Sepsis (2 papers, 2021 to 2025). Sepsis is defined as life-threatening organ dysfunction caused by a dysregulated host response to infection. "Conversely, lower expression of CKAP4 and PLEKHO1 also associates with increased sepsis severity, suggesting a complex, possibly non-linear interaction in their regulatory role." (PMID 40665987, 2025). "AKT1, top up- (FKBP5, SORT1, VNN1, and CST7) and downregulated (PRR5L, SH2B3, SULF2, PLEKHO1, and PTPN6) genes in sepsis were validated using RT-PCR." (PMID 33959663, 2021). "We observe a clear relationship between gene expression and sepsis severity based on the plasma analysis from GSE49757 and the coefficient signs for the genes NONO, CKAP4, PLEKHO1, and BMP6." (PMID 40665987, 2025). "While literature links NONO, FCAR, BMP6, RNF4, and RNASE2 to sepsis or Systemic Inflammatory Response Syndrome (SIRS), their interactions and the roles of PLEKHO1, OGFOD3, and CKAP4 in sepsis are less documented." (PMID 40665987, 2025). "Using our new plasma data (11 septic shock samples and 21 sepsis samples), the combinations of five genes (NONO, CKAP4, FCAR, PLEKHO1, BMP6) reached an overall accuracy of 93.75%, with a sensitivity of 81.82% and a specificity of 100.00%." (PMID 40665987, 2025). "Among all sepsis patients, the expression patterns of CKAP4 and PLEKHO1 do not show significant linearity, further supporting the idea that certain genes contribute uniquely to disease progression depending on their interaction networks and expression thresholds." (PMID 40665987, 2025).
triple-negative breast carcinoma (1 paper, 2016). An invasive breast carcinoma which is negative for expression of estrogen receptor (ER), progesterone receptor (PR), and human epidermal growth factor receptor 2 (HER2). "It is relevant that 9 tumors have a deletion of two genes previously related to cancer progression such as PLEKHO1 a negative regulator of the mitogenic PI3K/AKT signaling pathway and APH1A which loss of expression has been associated to poor survival in triple negative breast cancer patients." (PMID 26979459, 2016).
tumor (13 papers, 2017 to 2024). "Casein kinase 2-interacting protein-1 (CKIP-1, also known as PLEKHO1) inhibits tumor growth by causing inactivation of serine/threonine kinases and self-degradation of Smurf1, which is a potential oncogenic target in various tumor cells." (PMID 35449571, 2022). "PLEKHO1 might potentially affect the tumor immune microenvironment and could therefore be a novel target of immunotherapy." (PMID 35127943, 2022). "The findings presented here reveal that PLEKHO1 is a candidate tumor suppressor in cancer cells." (PMID 28881724, 2017). "During tumor progression, CAPZA1, GRB2, NF2EL3, PLEKHO1, SIGLEC1, and UBE2Z were expressed at higher levels in late-stage KIRC, whereas EMX2, FUCA1, IMPA2, and RORC were expressed at higher levels in early-stage KIRC." (PMID 35127943, 2022). "CAPZA1, HLA-E, IMPA2, NFE2L3, PLEKHO1, SIGLEC1, and UBE2Z were expressed at higher levels in tumor tissues, whereas EMX2, FGL2, FUCA1, and GRB2 were expressed at lower levels in tumor tissues." (PMID 35127943, 2022). "FGL2, FUCA1, PLEKHO1, and SIGLEC1 were highly expressed in DC and might influence its number in tumor." (PMID 35127943, 2022).
infection (1 paper, 2023). The state of being infected such as from the introduction of a foreign agent such as serum, vaccine, antigenic substance or organism. "To examine how Plekho1-deficient GC-Tfh cells may regulate GC B cell responses, we transferred Plekho1-CRISPR naïve OT-II cells into the Bcl6f/fCD4-CreTg recipient mice followed by PR8-OVA infection." (PMID 37330549, 2023).
PLEKHO1 also shares sentences with these, for which no sentence is quoted: cancer (7 papers); Atrophy (4); chronic heart failure (3); heart failure (3); lung carcinoma (3); atherosclerosis (2); diabetic nephropathy (2); diabetic retinopathy (2); glioma (2); non-small cell lung carcinoma (2); osteosarcoma (2); autoimmune disease (1); breast carcinoma (1); cholangiocarcinoma (1); colorectal cancer (1); coronary heart disease (1); diabetes (1); epithelial carcinoma (1); glioblastoma (1); heart disease (1); Hypertension (1); hypertrophy (1); immune disorders (1); malignant lymphomas (1); ovary cancer (1); papillary thyroid carcinoma (1); postmenopausal osteoporosis (1); renal fibrosis (1); rheumatoid arthritis (1); septic shock (1).
A further 2 diseases each share a sentence with PLEKHO1 in 1 paper.